PIK3CA (phosphatidylinositol-4,5-bisphosphate 3-kinase catalytic subunit alpha)
Diseases named in the same sentence as PIK3CA in open-access papers (continued):
Sharing a sentence is not in itself a finding about the gene and the disease.
cancer (continued). "Gain of function mutations in constituents of this pathway, amplification of PIK3CA and AKT, overexpression of AKT and inactivating mutations or loss of PTEN are involved in the aberrant activity of this signaling pathway and subsequent progression of cancer {Simpson, 2015 #155}." (PMID 35964082, 2022). "The current state of research postulates that PIK3CA-mutation-dependent activation of AKT phosphorylates and activates ER leading to transcriptional activity of ER in an oestradiol-independent manner and consecutively to preferential growth of ER-positive cancer." (PMID 36279023, 2022). "Moreover, in some cancers of the BM2 sub-type the presence of PIK3CA mutations is not sufficient to activate the KRAS/AKT and mTOR/protein translation pathways." (PMID 36079062, 2022). "Furthermore, data in the literature indicate that activating mutations of PIK3CA, detected in many cancers, do not occur at high frequency in primary cSCC." (PMID 33808215, 2021). "Similarly, the genes for proofreading polymerases POLE and POLD1 are mutated in 7.5% and 4.5% of PIK3CA mutated cancers versus 2.2% and 0.6% of PIK3CA non-mutated cancers." (PMID 33435133, 2021). "In addition, the PIK3CA pathway regulates angiogenesis and the immune response to cancer." (PMID 33987081, 2021). "PIK3CA variants were more frequent but not restricted to HR-positive cancers." (PMID 34504096, 2021). "Moreover, the increase of ROS levels in PTEN-deficient HCC1569 cells or PIK3CA mutant-HCC1954 cells could be their Achilles’ heel, since it has been reported that high levels of active AKT could increase the susceptibility of cancer cells to oxidative stress." (PMID 32438775, 2020). "The AUROC did not correlate with PIK3CA mutation rates of each cancer type." (PMID 33166334, 2020). "In addition, gene mutations, such as PIK3CA and BRAF, may also have an impact on the benefits of aspirin use for several types of cancer." (PMID 32545461, 2020). "Thus far, high-throughput resequencing efforts worldwide aimed at identifying unknown somatic mutations in human cancer have already revealed that yet uncharacterized mutations in KRAS, NRAS, BRAF, PIK3CA, PTEN and other cancer genes are highly prevalent." (PMID 32620824, 2020). "It is unclear whether the lack of PIK3CA mutations in the clonal IDP/carcinomas is by chance due to the limited cases (n = 6) or reflects an intrinsic biological difference in carcinoma arising from an IDP." (PMID 32195332, 2020). "However, it is worth noting that H1047R mutation is the main mutation form of PIK3CA, whether in TCGA GC cohort or MSK pan-cancer cohort." (PMID 31781598, 2019). "Moreover, EGFR, PIK3R1, and PIK3CA are well-known cancer genes." (PMID 31024613, 2019). "Indeed, PIK3CA, which encodes the α subunit of PI3K, is also frequently altered in various cancers." (PMID 31454965, 2019).
cancer (continued). "In addition, PIK3CA or BRAF mutations were observed in seven cancer subjects and no non-cancer subjects." (PMID 31711466, 2019). "The non-mutated, wild-type PIK3CA gene is also frequently amplified in cancer, such as in lung squamous carcinoma where this occurs as part of amplification of the 3q genomic locus, the most common genomic aberration in this cancer." (PMID 31374965, 2019). "Moreover, a few studies have also shown that in cancer, PIK3CA and PTEN mutations are not necessarily mutually exclusive but that their concomitant alterations can have biological effects and therapeutic implication." (PMID 30999672, 2019). "Early clinical trials suggest PIK3CA mutations are a biomarker of such dependence, but that may still not capture the whole repertoire of cancers likely to benefit from these drugs." (PMID 31552290, 2019). "Specific PIK3 inhibitors are being employed in clinical trials of advanced stage cancers, and the positive overall response rates and progression-free survival rates being observed for PIK3CA-mutant tumors may make this a useful therapeutic strategy for a subset of craniopharygiomas." (PMID 31712784, 2019). "Thus, although PIK3CA mutations are very common in cancers, none of the cancer types enriched for such mutations (e.g., endometrial and breast) have been reported in PROS." (PMID 30197175, 2018). "Aspirin inhibited cell growth in all cancer cell lines regardless of mutational background, however, the effects were exacerbated in cells with PIK3CA mutations, which might explain the different effects of aspirin on cancers." (PMID 29534696, 2018). "The discovery of activating PIK3CA mutations in PROS has not only yielded a new target for much-needed precision therapies, but has also exposed gaps in our understanding of PI3K signaling in human cancer and embryonic development (see Outstanding Questions and Box 1)." (PMID 30197175, 2018). "However, such cisplatin-induced transcriptional regulators of PIK3CA and their impact on cancer stem cell population in resistant cells are largely unknown." (PMID 29169370, 2017). "However, the specific contribution of Pik3caH1047R-driven centrosome amplification in interaction of mutant PIK3CA with other cancer-promoting genetic lesions remains unknown." (PMID 29170395, 2017). "Furthermore, our study suggests a possible therapeutic benefit of pharmacologic disruption of the association between FOXO3a and 14-3-3 to sensitize PIK3CA-mutant cancers that do not respond to the combined therapy with inhibitors of PI3K and autophagy." (PMID 28036259, 2017). "The synergistic effect of BKM120 and HCQ combination in PIK3CA-mutant cancer cells is not related to the type of PIK3CA mutation and other factors seem to be involved because Caski and MCF7 with the same PIK3CA mutation (E545K) showed different responses to the combined treatment of BKM120 and HCQ." (PMID 28036259, 2017). "Although no overall association was identified between the activation of the mTOR pathway and the presence of functional mutations in the PIK3CA and PTEN genes, this may have been a reflection of differences between different cancer types within the limited sizes of those sample populations." (PMID 29137436, 2017). "In other words, ESCC patients with a PIK3CA mutation constitute a subgroup only in terms of the applicability of a PI3K inhibitor, since emerging evidence suggests that patients with PIK3CA-mutated cancer might benefit from treatment with PI3K inhibitors." (PMID 28068934, 2017). "Therefore, we examined the effects of AG1478 on cancer cells with different PIK3CA gene statuses." (PMID 28134774, 2017). "Although varying frequency of activating somatic mutations across different populations is known in the literature for EGFR,22KRAS,23BRAF,24 and PIK3CA25, 26 in lung, colorectal, and other cancers, absence of PIK3CA mutations in Indian cases of RMS is surprising." (PMID 27562493, 2016).
cancer (continued). "Together, these results suggest that PIK3CA mutation and expression is associated with PTEN expression, which again may be a reflection of the competition that occurs between pro-cancer molecular programs and anti-cancer cellular responses." (PMID 27589846, 2016). "However, cancer cells display an intrinsic heterogeneity, hence it is unclear if trametinib and rapamycin promote apoptosis in Detroit 562 because these cells express mutant PIK3CA or if this response is due to cell-dependent variations." (PMID 26882569, 2016). "Therefore, the down-regulation of cyclin D1 by resibufogenin may be also useful to overcome the resistance of MEK inhibitor in malignant tumors with mutations in both KRAS and PIK3CA." (PMID 26121043, 2015). "It is expected that ddPCR may have good application prospects in molecular cancer diagnosis, for example in the study of phosphoinositide-3-kinase, catalytic subunit α (PIK3CA), MET proto-oncogene (MET; hepatocyte growth factor) and Kirsten rat sarcoma viral oncogene homolog (K-RAS)." (PMID 25780439, 2015). "Interestingly, PIK3CA mutations occurred almost always in combination with HRAS mutations (p < 0.0001), only one case of carcinoma ex pleomorphic adenoma (SDC) carried a PIK3CA mutation without a simultaneous HRAS mutation." (PMID 26053092, 2015). "However in this study, no mutations at PIK3CA were detected in the claudin-low cancers, so the roles of PIK3CA mutations in these cancers are not clear." (PMID 25051360, 2014). "Importantly, PIK3CA mutations have also been found in the non-tumoral tissue of several cancer patients." (PMID 25295225, 2014). "PI3K activation, e.g., by activating mutations of PIK3CA encoding the catalytic subunit, p110alpha, leads to an activation of AKT, a serine-threonine kinase, which is present in three different isoforms (AKT1-3) in human cancer and leads to increased cellular growth and survival of cancer cells." (PMID 24036443, 2013). "While the traditional, gene centric view of mutation does not consider the location of mutations within the PIK3CA gene, our domain-centric approach captures the functional modularity of protein domains and enables us to reveal specific domains critical to the cancer development process." (PMID 22759657, 2012). "Despite activation of the PI3K-AKT-mTOR pathway being a common feature of many cancers, and activation of this pathway being associated with regulation of a number of metabolic effects, comprehensive profiling of the consequence of PIK3CA mutations on metabolic dependencies has not been studied." (PMID 23028762, 2012). "In addition to activating mutations, PIK3CA gene amplification has also been implicated in cancer and has been associated with increased PI3K signaling, for instance, in ovarian and cervical cancers." (PMID 20804548, 2010). "Furthermore, based on our results, PIK3CA targeting might be a rational approach to combine with anti-inflammatory cancer therapy." (PMID 18335034, 2008). "From a prognostic standpoint, long-term prospective, blinded randomised trials could be performed to determine if the presence or absence of PIK3CA mutations have any correlation with clinical outcome in various cancer types." (PMID 16449998, 2006). "Meanwhile, it is well understood that accelerated cancer progression can be attributed to excessive activation of PI3K subunit, including PIK3CA, and many PI3K inhibitors are used for cancer therapies in clinical trials." (PMID 41538663, 2026). "Drugs bound to albumin selectively target cancer cells with upregulated macropinocytosis, a process driven by constitutively hyper‐activated EGFR/RAS/PIK3CA signaling, which is common in HNSCC." (PMID 41521502, 2026).
cancer (continued). "Drugs bound to albumin selectively target cancer cells with upregulated macropinocytosis, an endocytic nutrient‐scavenging process driven by constitutive hyper‐activation of the EGFR/RAS/PIK3CA signaling and Syndecan1 pathways." (PMID 41521502, 2026). "Several other cancer-related alterations were detected at lower frequencies, including alterations in PTEN, PIK3CA, APC, and CTNNB1 genes." (PMID 40699829, 2025). "Rearrangement of TBL1XR1 (3q26.32) have been identified in various cancers involving different genes, including RARA (17q21), HMGA1 (6p21), TP63 (3q28), RET (10q11.2), and PIK3CA (3q26.32)." (PMID 41123735, 2025). "The PI3K/Akt pathway is one of the most frequently altered pathways in cancer, usually due to genomic alterations in EGFR, PIK3CA, AKT, and PTEN." (PMID 40508087, 2025). "While the PI3K/AKT/mTOR axis is well-characterized in cancer metabolism and EMT, most studies focus on canonical isoforms like PIK3CA or PIK3CB." (PMID 41362647, 2025). "These proteins are involved in critical cancer-related pathways, including SRC in the MAPK signaling pathway, ABL1 in JAK/STAT signaling, PIK3CA in the PIK3-Akt pathway, and MAPK3 in the Ras signaling pathway." (PMID 40105884, 2025). "Specifically, for GBM (adults) and GBM_DE (children), four genes (CASP8, PIK3CA, PTEN, LPAR4) related to pathways in cancer are identified." (PMID 40768543, 2025). "Indeed, it seems that increased sensitivity to PI3K/Akt pathway inhibitors is not universal to all types of cancer or to all classes of inhibitors, and the presence of different PIK3CA mutations might lead to distinct inhibitor sensitivities." (PMID 40508087, 2025). "The evaluation of PPI networks related to miRNAs involved in cancer further reinforced the central role of EGFR, CCND1, and PIK3CA, as they consistently emerged as the top three hub genes." (PMID 40764607, 2025). "Furthermore, we found that cancer cells exhibited dominant expression of the mutated alleles, including those in the proto-oncogene KRAS (e.g., c.35G>T in CRC07, c.436G>A in HTCRC01 and c.38G>A in HTCRC05), KLF5 (c.935C>T in CRC07) and PIK3CA (c.2836G>T in CRC09)." (PMID 40702779, 2025). "Despite this challenge, the current report provides evidence that PIK3CA-specific T cells can be identified and their TCR can be isolated from antigen-experienced TIL and PBL of patients with cancer." (PMID 41410746, 2025). "These included some notable oncogenes known to be drivers in the found cancer types, such as PIK3CA in BRCA, BRAF in SKCM, and EGFR in LGG and LUAD, and KRAS across several cancers including PAAD, LUAD and COAD." (PMID 41415395, 2025). "It has been reported that the E3 ubiquitination ligase WWP1 can ubiquitinate PTEN, inhibit its activity, and activate the PIK3CA/AKT signaling pathway to increase the occurrence and development of cancer." (PMID 40075587, 2025). "Key genes such as COL1A1, COL4A1, PIK3CA, PIK3R1, and mTOR were found to be overexpressed, correlating with increased cancer aggressiveness." (PMID 39850811, 2024).
cancer (continued). "Furthermore, combined amplification of PIK3CA and SOX2 is emerging as a valuable and easy-to-implement tool for cancer risk stratification that may complement histopathological diagnosis to distinguish high-risk patients more accurately, and to ultimately improve personalized treatment decisions." (PMID 38473941, 2024). "•PIK3CA and GATA3 were the main cancer driver genes in luminal samples, and candidate drivers were GRHL2 and SMURF2." (PMID 39208653, 2024). "Three other genes were found to be significant prognostic factors for overall survival in more than one cancer type, NF1, PIK3CA and PTEN." (PMID 39277826, 2024). "In luminal samples, PIK3CA and GATA3 were the main cancer drivers, and other drivers were GRHL2 and SMURF2." (PMID 39208653, 2024). "An OCSCC cohort more than twice the size of the TCGA cohort allowed us to find additional cancer driver genes that are frequently affected in CNA-quiet OCSCC, notably PIK3CA, RAC1, and TERT, besides the previously established HRAS and CASP8." (PMID 39428388, 2024). "The nCounter v2 Cancer CN Assay panel consists of 87 target genes and is intended for CNV genotyping of tumors with various profiles of aberrations in the PIK3CA, AKT, PTEN, BRCA, ERBB2, and MYC genes." (PMID 39409874, 2024). "We corroborated, using novel ways of correlating absolute SCNA with transcriptomics, that in our organoid models, the correlation was highest for MYC, PIK3CA, and AKT2 reinforcing their putative role as potential targetable cancer drivers." (PMID 37166279, 2023). "MutSigCV analysis identified CDC27, PIK3CA, GATA3, CDH1, CTBP2, and CRIPAK as common cancer driver genes across both Ki67 expression groups (ZF13)." (PMID 37454130, 2023). "For NECE, five genes were mutated in 80% of patients, including PIK3CA, FAT3, MUC2, PLEC, and TTN, among which PIK3CA and FAT3 belong to the COSMIC Cancer Gene Census gene tier 1 and 2, respectively." (PMID 37920164, 2023). "In one study, cancer driver genes ARID1A, PIK3CA, KRAS, and PPP2R1A were identified in 21% of endometriotic lesions." (PMID 37573406, 2023). "A number of pivotal cancer-related genes, including HER2, CCND1, PIK3CA, and CDKN2A, were pinpointed within the top 500 genes in both the differential signaling network and the analysis of differentially expressed genes." (PMID 38087279, 2023). "The most prevalent altered cancer-related genes were CTNNB1 (16%) and ZNRF3 (16%), followed by EGFR (11%), JARID2 (11%), KMT2B (11%), KMT2C (11%), NSD1 (11%), PIK3CA (11%), SH2B3 (11%), and UBR5 (11%)." (PMID 38023213, 2023).